ALB (albumin)
Diseases named in the same sentence as ALB in open-access papers (continued):
Sharing a sentence is not in itself a finding about the gene and the disease.
Opportunistic infection (10 papers, 2004 to 2025). An infection that is caused by a pathogen that would generally not be able to cause an infection in a host with a normal immune system. "In Model 1, the presence of nutritional risk, low lymphocyte counts, low serum albumin levels and elevated HbA1c levels were identified as significant risk factors for opportunistic infections(P<0.05)." (PMID 39866736, 2024). "This study identified nutritional risk, duration of HIV infection, HbA1c and albumin as significant risk factors and predictors of opportunistic infections in HIV-DM patients, further highlighting the importance of nutritional screening and good glucose control." (PMID 39866736, 2024). "Low albumin level, indicating poor nutritional status and impaired immune function, may increase susceptibility to opportunistic infections, which could subsequently contribute to increased mortality risk." (PMID 39866736, 2024). "In our study, serum albumin level was identified as both a significant predictor and protective factor against opportunistic infections." (PMID 39866736, 2024). "Previous studies have primarily focused on a low albumin level as a mortality risk factor in HIV-infected patients, with both low albumin level and opportunistic infections being independent predictors of poor survival." (PMID 39866736, 2024). "Logistic regression analysis identified nutritional risk, duration of HIV infection, HbA1c, albumin, and CD4+ T cell counts as significant risk factors and predictors of opportunistic infections." (PMID 39866736, 2024). "Laboratory analyses demonstrated reduced levels of nutritional indicators in the opportunistic infections group, including albumin (ALB) and total protein, accompanied by an increased prevalence of nutritional risk." (PMID 39866736, 2024). "Our findings establish a direct link between albumin level and the occurrence of opportunistic infections, suggesting a potential mechanistic pathway." (PMID 39866736, 2024). "This study identified significant risk factors for opportunistic infections through multifactorial logistic regression analysis, including nutritional risk, duration of HIV infection, HbA1c levels, lymphocyte counts, albumin level, and CD4+ T cell counts." (PMID 39866736, 2024). "It is because that the decrease of ALB is one of the signs of low immunity and commonly noted in patients with opportunistic infections." (PMID 33912176, 2021). "The mortality of patients with severe drug eruption, drug hypersensitive history, CD4+ T cell count ≤200 cells/μL, opportunistic infection, viral load ≥1 × 102 copies/mL, low ALB level or decreased RBC and Hb was significantly increased." (PMID 27796328, 2016). "This interconnection highlights the dual clinical significance of serum albumin monitoring and maintenance in HIV-infected patients, serving as both a preventive measure against opportunistic infections and a potential determinant of survival outcomes." (PMID 39866736, 2024). "The deceased group and survival group had statistically significant differences in ANC, IgG, SCr, serum albumin, proteinuria, cardiopulmonary involvement, SLEDAI score, and prevalence of opportunistic infection (all p < 0.05)." (PMID 34660641, 2021). "There were no incidences of opportunistic infections, effects on kidneys, or TEAEs related to reductions in albumin or plasma proteins during the 18-week treatment period or the 7-week follow-up period." (PMID 41074934, 2025). "There were no incidences of aseptic meningitis, opportunistic infections, effects on kidney, or TEAEs related to reductions in albumin or plasma proteins." (PMID 41074934, 2025). "Duration of HIV infection (OR=0.576, 95%CI:0.444-0.747), albumin (OR=0.956, 95%CI:0.936, 0.976) and CD4+T cell counts (OR=0.999, 95%CI: 0.998,1.000) showed negative associations with opportunistic infections (P<0.05)." (PMID 39866736, 2024).
Opportunistic infection (continued). "Thus, ANC, 24h-UPro, SCr, IgG, albumin, SLEDAI, opportunistic infections, and cardiopulmonary involvement were analyzed in the multivariate analysis." (PMID 34660641, 2021).
pancreatic insufficiency (10 papers, 2015 to 2025). "Along with hypovascularity, decreasedexpression of albumin would worsen pancreatic exocrine insufficiency and chemotherapeuticdrug delivery in PDAC patients." (PMID 33884102, 2021). "A great proportion of participants had pancreatic insufficiency (86.8%), whereas none of the children were on enteral nutrition or exhibited low serum albumin levels." (PMID 33291524, 2020).
pyometra (10 papers, 2014 to 2025). "Albumin might have a diagnostic value in dogs with pyometra and more severe disease (septic peritonitis or septic shock), but this needs to be further studied." (PMID 25430894, 2014). "Conversely, albumin is a sensitive marker of therapeutic evolution for both protocols for pyometra in bitches." (PMID 41463815, 2025). "Serum fructosamine was previously considered a poor indicator of insulin resistance during diestrus, and reduced serum albumin due to inflammatory-mediated catabolism that was documented in nearly a third of the bitches with pyometra turns it even worse." (PMID 38539988, 2024). "Using SPE, serum proteins in both dogs with pyometra and control dogs were separated as five fractions of albumin and α1-, α2-, β-, and γ-globulins." (PMID 33732740, 2021). "By SPE analysis, decreased levels of albumin and elevated levels of α2-globulin and β-globulin were noted in dogs with pyometra." (PMID 33732740, 2021). "In conclusion, changes in the serum protein electrophoresis profile were noted in dogs with pyometra, described as reduced albumin and elevated α2- and β-globulin." (PMID 33732740, 2021). "Among fractions in SPE, significantly reduced albumin and elevated α2- and β-globulins were found in dogs with pyometra compared to the control dogs." (PMID 33732740, 2021). "Meanwhile, Hb, PCV, Lymphocytes and Albumin were significantly decreased in dogs with pyometra compared to healthy group." (PMID 25636335, 2015). "Thus, it may be inferred that therapeutic modalities for pyometra exert distinct effects on the blood albumin profile, as surgical trauma itself constitutes an inflammatory stimulus." (PMID 41463815, 2025). "In line with this, queens affected by pyometra showed higher serum levels of acute phase proteins and FRAP values, together with lower values of total serum thiols; this last finding is an expression of an SH-group-mediated antioxidant barrier and is associated with lower albumin serum content." (PMID 36670793, 2023). "In the present study, reduced levels of albumin, elevated levels of α2 globulins β-globulin and increased APP concentrations were noted in canine pyometra." (PMID 33732740, 2021). "In pyometra, the PCV, Hb, Lymphocyte and Albumin concentrations were decreased whereas WBC, Neutrophils, Band neutrophils, and Monocytes were increased in dogs with pyometra compared to healthy dogs." (PMID 25636335, 2015). "Our findings differ from those reported by Hadzimusic and Alagic, who observed no alterations in albumin levels following surgical treatment of bitches with pyometra." (PMID 41463815, 2025). "In addition, significant decrease in the levels of glucose, cholesterol, albumin, Ca, phosphorus, sodium, TAC, GPx, and superoxide dismutase was observed in the pyometra group." (PMID 33776298, 2021). "Conversely, the circulating profile of albumin, a negative acute phase protein, proved to be a sensitive and practical marker of therapeutic evolution in both the aglepristone protocol and when it was combined with prostaglandin for pyometra in bitches." (PMID 41463815, 2025). "Fructosamine fails to evidence insulin resistance in bitches with pyometra, and showed reduced levels compared with bitches in diestrus, a finding considered to be the result of the lower albumin serum concentration levels observed in the bitches with pyometra." (PMID 38539988, 2024). "Therefore, we suggest that the efficacy of medical therapy for pyometra may be monitored through serial evaluation of serum albumin, an assessment not typically indicated in surgical treatment protocols." (PMID 41463815, 2025).
sickle cell disease (10 papers, 2011 to 2024). Sickle cell anemias are chronic hemolytic diseases that may induce three types of acute accidents: severe anemia, severe bacterial infections, and ischemic vasoocclusive accidents (VOA) caused by sickle-shaped red blood cells obstructing small blood vessels and capillaries. "Age and hemoglobin adjusted association between serum albumin and sickle cell clinical variables in adults with sickle cell disease in validation cohort (OMG)." (PMID 32776978, 2020). "Age and hemoglobin adjusted association between serum albumin and sickle cell clinical variables in adults with sickle cell disease in test cohorts." (PMID 32776978, 2020). "It has revealed a biomarker, microglucosuria, which could be used as well as the urinary albumin/total protein ratio in association with proteinuria for screening kidney dysfunction in sickle cell anemia patients." (PMID 36409722, 2022). "25.9% with HbSS and 10.8% with HbSC disease had microalbuminuria (urine albumin/creatinine ratio = 30–300 mg/g of creatinine) whereas 16.5% of HbSS and 2.7% of HbSC disease had macroalbuminuria (urine albumin/creatinine ratio>300 mg/g of creatinine)." (PMID 21533141, 2011).
thyroid cancer (10 papers, 2010 to 2025). "This study is the first to evaluate the association between bilirubin subtypes (total, indirect, and direct bilirubin) and thyroid cancer risk using the ALBI (Albumin-Bilirubin) and PALBI (Platelet-Albumin-Bilirubin) indices." (PMID 40723913, 2025). "The observation of an association between low levels of albumin and the risk of developing a thyroid cancer suggests the importance of inflammation as one of the mechanisms underlying carcinogenic development." (PMID 29416653, 2018). "In the AMORIS study, we found evidence for an inverse association between serum albumin levels and the risk of developing a thyroid cancer." (PMID 29416653, 2018). "We further modelled the potential association between serum albumin and the risk of developing a thyroid cancer through a dose-response curve with restrictive cubic splines." (PMID 29416653, 2018). "There was a positive association between lower albumin levels and risk of developing thyroid cancer [Hazard Ratio for albumin ≤ 40 g/L: 1.50 (95% Confidence Interval = 1.04–2.16)]." (PMID 29416653, 2018). "Lower values of serum albumin were associated with the risk of developing a thyroid cancer [HR for albumin ≤ 40 g/L: 1.50 (95% CI = 1.04–2.16)] in a multivariate model." (PMID 29416653, 2018). "This study is the first cohort-based investigation to evaluate the association between bilirubin subtypes (total, indirect, and direct bilirubin) and thyroid cancer risk using the ALBI (Albumin-Bilirubin) and PALBI (Platelet-Albumin-Bilirubin) indices in a general population." (PMID 40723913, 2025). "In a case-control study with 114 cases of thyroid cancer and 333 matched controls from the Janus serum bank in Norway, a positive association between serum albumin levels and the risk of developing papillary carcinoma and follicular carcinoma of the thyroid was found." (PMID 29416653, 2018). "The observed association between albumin and the risk of developing a thyroid cancer may support the well-established concept of low serum albumin as a marker of poor health status." (PMID 29416653, 2018). "In an orthotopic xenograft mouse model using human thyroid cancer patient tissue, dual imaging for detection of TC cells was possible with iodinated gold nanoclusters synthesized via bovine serum albumin and chloramine-T." (PMID 34439219, 2021). "We explored the risk of developing a thyroid cancer by assessing serum biomarkers that are commonly measured in clinical practice and are indicative of inflammation (CRP, albumin, haptoglobin and leukocytes) in a large Swedish cohort study." (PMID 29416653, 2018). "Specifically, the ALBI index may capture the antioxidative interaction between indirect bilirubin and albumin, which could play a protective role against thyroid cancer development." (PMID 40723913, 2025). "Apart from albumin, none of the serum markers of inflammation studied showed a link with the risk of developing thyroid cancer–suggesting that the role of inflammation may be more complicated and requires assessment of more specialised measurements of inflammation." (PMID 29416653, 2018). "In 2010, Laney and coworkers evaluated serum calcium, creatinine, albumin, and 25-hydroxy vitamin D (25-OH-D) in patients with thyroid nodule, thyroid cancer in remission, and active thyroid cancer and found that serum 25-OH-D was not different between groups." (PMID 28092021, 2017).
alcoholic hepatitis (9 papers, 2003 to 2025). Acute hepatitis resulting from ingestion of alcohol. "• Albumin dialysis results in favourable effects in patients with severe alcoholic hepatitis, because hepatic encephalopathy improved in all cases." (PMID 19175915, 2009). "The aim of this study was to assess the effects of albumin dialysis on hepatic encephalopathy and circulating levels of amino acids in severe alcoholic hepatitis." (PMID 19175915, 2009). "Albumin dialysis resulted in a 17% increase in the Fischer ratio in patients with alcoholic hepatitis and a 3% decrease in patients with resistant pruritus (p < 0.05)." (PMID 19175915, 2009). "The results of the current study clearly indicate that albumin dialysis is able to induce favourable effects in patients with severe alcoholic hepatitis." (PMID 19175915, 2009). "The mechanism by which albumin dialysis decreases phenolic aromatic amino acids in patients with severe alcoholic hepatitis is unknown." (PMID 19175915, 2009). "Moreover, the Fischer's ratio, which was significantly lower in patients with alcoholic hepatitis (1.32 ± 0.08) than in controls (3.20 ± 0.16), increased by 17% after albumin dialysis (p < 0.02) because of a significant decrease in phenolic aromatic amino acids (193 ± 17 μM to 165 ± 9 μM, p = 0.04)." (PMID 19175915, 2009). "Other conditions considered precipitating factors are less common, including acute alcoholic hepatitis, major surgery, TIPS insertion, or inadequate paracentesis without albumin substitution." (PMID 37509478, 2023).
Atrophy (9 papers, 2016 to 2024). Any weakening or degeneration, especially through lack of use. "Higher tubular atrophy and interstitial fibrosis scores were also associated with a greater albumin-to-creatinine ratio, as observed in the canonical correlation analysis." (PMID 27276392, 2016). "And finally, the association of lower albumin levels with anti-EMA and atrophy positivity, as well as the association of anti-EMA positivity with HP, and atrophy positivity were revealed in patients with dyspepsia." (PMID 37546692, 2023). "In the present study, liver function reserve was worse and ChE and albumin levels were lower in the severe atrophy group than in the mild atrophy group." (PMID 35444161, 2022). "In contrast, the Post values of liver function reserve including Child–Pugh and ALBI score, albumin, and ChE were significantly worse in the severe atrophy group than in the mild atrophy group." (PMID 35444161, 2022). "Correlation analysis revealed a slightly negative correlation between albumin and anti-EMA/atrophy positivity which means that lower albumin levels are associated with higher anti-EMA and atrophy positivity (p=0.037 and 0.001, respectively)." (PMID 37546692, 2023). "In HanSD rats, DOX caused bilateral cardiac atrophy and impairment of the liver synthetic function (see reduced plasma albumin levels) without affecting the whole body or other organs’ weight." (PMID 33302374, 2020). "Correlation analysis revealed an inverse correlation between albumin and anti-EMA/atrophy positivity whereas a positive correlation between anti-EMA and HP/atrophy positivity." (PMID 37546692, 2023).
biliary tract cancer (9 papers, 2014 to 2026). "Albumin in combination with other inflammatory markers has shown prognostic value in malignancy, including biliary tract cancer (BTC)." (PMID 41504962, 2026). "In our previous study, low albumin levels were responsible for poor prognosis in patients receiving DC immunotherapy for biliary tract cancers, and the same phenomenon was observed in this study on ROC patients." (PMID 25298213, 2014). "Previously, general inflammatory markers in plasma (CRP, albumin) were validated as independent negative prognostic factors for overall survival for patients with resectable biliary tract cancer (BTC)." (PMID 37404757, 2023). "Several studies have reported that preoperative indicators, such as serum albumin and CRP levels, as well as widely recognized tumor markers (CEA and CA 19-9) may also serve as prognostic indicators of biliary tract cancer outcomes; however, the NLR and LMR scored over these factors in this study." (PMID 32321522, 2020).
chronic pancreatitis (9 papers, 2016 to 2025). A chronic inflammatory process causing damage and fibrosis of the pancreatic parenchyma. "For instance, AZGP1 and ALB were highlighted as potential diagnostic markers in chronic pancreatitis while ORM2 has been implicated in inflammatory pancreatic conditions." (PMID 41007761, 2025). "Other risk factors found were a low preoperative albumin level, a current smoking habit, and chronic pancreatitis." (PMID 33301071, 2021). "Notably, in our study, in contrast to cholinesterase neither albumin nor prealbumin changed during the intervention, which supports that these parameters are not suitable to monitor nutritional status in patients with chronic pancreatitis." (PMID 39440042, 2024). "The role of some factors might be inconclusive due to the lacking of enrolled studies, such as history of chronic pancreatitis, extended lymphadenectomy, PGA felt wrapping, and serum albumin levels." (PMID 28298641, 2017).
cystic fibrosis (9 papers, 2015 to 2026). Autosomal recessive disorder caused by pathogenic variants in the CFTR gene (cystic fibrosis transmembrane conductance regulator), which encodes a chloride and bicarbonate channel expressed in epithelial cells, and follow the diagnosis criteria. "For example, BMI and albumin have been reported to be independently associated with FEV1% predicted in children with cystic fibrosis." (PMID 37076819, 2023). "Associations between the C-reactive protein/albumin ratio and lung function, nutritional status, positive culture for Pseudomonas aeruginosa and hospitalization among patients with cystic fibrosis have been little investigated." (PMID 29267535, 2018). "Multicenter studies need to be conducted in order to evaluate the applicability of the C-reactive protein/albumin ratio among children/adolescents with cystic fibrosis in clinical practice." (PMID 29267535, 2018). "In pre-trial studies we assessed airway deposition in patients with cystic fibrosis with varying FEV1 severity with technetium-99m labelled human serum albumin of similar droplet size (3–4 μm, using a different nebuliser system) to the pGM169/GL67A formulation." (PMID 26149841, 2015). "No previous studies in which the C-reactive protein/albumin ratio was evaluated among children/adolescents with cystic fibrosis were found, although determination of C-reactive protein and albumin levels forms part of routine hospital evaluations." (PMID 29267535, 2018). "There is a lack of studies evaluating the C-reactive protein/albumin ratio among children/adolescents with cystic fibrosis." (PMID 29267535, 2018). "The median C-reactive protein/albumin ratio was also higher in the cystic fibrosis group, but the difference was not significant (P = 0.077)." (PMID 29267535, 2018).